IL6 (interleukin 6)
Diseases named in the same sentence as IL6 in open-access papers (continued):
Sharing a sentence is not in itself a finding about the gene and the disease.
tumor (continued). "Although other studies have shown that high NLR was related to the increasing of monocyte chemotactic protein-1, interleukin-1 receptor α (IL-1R-α), IL-6, IL-7, IL-8, IL-12 and IL-17 in peripheral blood, these cytokines could build and keep an immune microenvironment promoting tumor invasion." (PMID 28036275, 2017). "The fact that these three cytokines (IL-6, IL-1β, LCN2) were up-regulated in LuM cells indicates that these highly metastatic cells obtained through in vivo selection will be a useful resource for further studies on elucidating the mechanisms underlying cytokine-related tumor growth and metastasis." (PMID 28410227, 2017). "Moreover, IL-6 is a critical tumor promoter during early tumorigenesis in the CAC mouse model." (PMID 28938014, 2017). "Interestingly, IL-17A can promote tumor growth through an IL-6/STAT-3 signaling pathway." (PMID 28402963, 2017). "Therefore, measurement of IL-6 may be help to diagnose the tumor before therapy and predict the recurrence." (PMID 27659803, 2016). "Interestingly, TamR metastases were markedly enriched (∼30-fold) for CD133hi cells and had an increased expression of secreted/autocrine IL6 compared with the primary tumours (from the same mouse) or from both primary tumours and metastases from placebo-treated mice." (PMID 26858125, 2016). "More than a half a century after its discovery, novel roles for the IL6 signaling pathway in tumor formation and progression have been consistently uncovered, including roles in regulating the proliferation, migration, activation, morphology, and metabolic state of tumor cells." (PMID 27163161, 2016). "As NANOG can be induced by HIF and cytokines including interleukin-6, tumor microenvironments such as hypoxia and inflammation may (epigenetically) reprogram non-CSCs to the CSC state through NANOG by similarly antagonizing/engaging lineage-specific TF signaling complexes." (PMID 27867534, 2016). "Based on these results, one could speculate that even though a greater number of the bacterium would considerably increase the secreted levels of IL-6 and IL-8, an infection with a smaller number of P. acnes may over time be enough to contribute to a micro milieu rich in tumor supporting mediators." (PMID 27284286, 2016). "Therefore, we concluded that IL-6 promoted tumour development." (PMID 26623559, 2016). "We then determined whether the elevated IL-6 in tumor-bearing mice accounted for the suppression of hepatic Ppara and ketogenesis by administering neutralizing anti-IL-6 antibody to pre-cachectic mice with C26 tumors for 72 hr, during which TFR was imposed for the final 24 hr." (PMID 27829137, 2016). "We also assessed whether inhibition of the IL-6 signaling pathway affected tumor volume." (PMID 27068103, 2016). "Therefore, as shown in other models, IL-6 within the local tumor microenvironment of people with CRC, may modulate macrophage function." (PMID 27195119, 2016). "We demonstrate that AML cell-derived R-2HG may be helpful for the establishment of a tumor-promoting bone marrow stromal niche for AML cells by producing growth-proliferating cytokine (IL-6) and enhancing cell-cell interaction (VLA-4/VCAM-1) to increase proliferation and chemoresistance." (PMID 27577048, 2016). "Many lines of evidence demonstrated that IL-6 exhibits tumor-promoting actions including regulation of tumor growth and chemo-resistance, induction of epithelial-mesenchymal transition and promoting angiogenesis as well as lymphangiogenesis, which contribute to tumor metastasis." (PMID 27383632, 2016). "IL6 present in the tumor microenvironment may play a protective role for the cancer cells." (PMID 27366950, 2016). "Therefore, targeting the IL-6/STAT3 pathway in both tumor cells and their stromal fibroblasts could present great therapeutic approach for more efficient eradication of tumors." (PMID 27248826, 2016).
tumor (continued). "Several pro-inflammatory cytokines, such as IL-1, IL-6 and IL-8, participate in development of chronic inflammation have also been proven to induce and maintain procarcinogenic inflammatory microenvironment at the initiation of malignant transformation and tumor progression." (PMID 27738346, 2016). "Taken together, out results suggest that this MEK inhibitor is not protective in LLC cancer cachexia despite lowering IL-6 levels, and further that it might exacerbate tumor-induced weight loss." (PMID 28149280, 2016). "However, monoclonal antibodies targeting VEGF and EGFR may be un-sufficient to controlling the activity of other signaling pathways such as IL6/STAT3 signaling, which may exemplify the underlying mechanism of anti-tumor resistance." (PMID 27729020, 2016). "Besides its effects on tumor cells, MSCs themselves are also the target of IL-6." (PMID 27531897, 2016). "Tumor metastasis comprises different processes that lead tumor cells move away from the tumor to a distant location and some authors suggested that stromal cells regulate the production of various factors implicated in metastasis process such as COX2, TNF-α, IL-6, and IL-11." (PMID 27195300, 2016). "In addition, IL-6 suppression reduces tumor self-seeding by circulating tumor cells in OS." (PMID 27888627, 2016). "Furthermore, we recently found that the frequency of CD4+ T cells expressing Foxp3 was significantly decreased in the tumor but not in the spleen after HSCT and that the decrease in Tregs was dependent on interleukin‐6 (IL‐6) produced by dendritic cells in the tumor." (PMID 26589884, 2016). "Interestingly, we observed several pro-inflammatory cytokines such as IL-17A, IL-6 and TNF-α that were downregulated (at an mRNA level) in mda-9-deficient naïve lungs, suggesting a potential impairment of pro-tumorigenic responses to invading tumor cells." (PMID 27341128, 2016). "Furthermore, residual vital tumour cells may have been temporary suppressed by the local IL-1- and IL-6-mediated immune response after RFA." (PMID 27387188, 2016). "In addition, blocking IL-6 or IL-6R in prostate cancer and methylcholanthrene-induced skin squamous cell carcinoma mouse models resulted in the prominent reduction of MDSCs infiltrating tumors and in the suppression of tumor development." (PMID 27827871, 2016). "Furthermore, IL6 is a cytokine that is not only involved in inflammation and infection responses but also in the regulation of metabolic, regenerative, and neural processes as well as tumor progression." (PMID 27163161, 2016). "Hence, our data suggests that downregulation of TNF-α, IL-6 and IL-8 cytokines could account, at least partly, for the inhibition of tumor growth and metastasis mediated by Rhus coriaria." (PMID 26888313, 2016). "Evidence indicated that MCP-1 and IL-6 could assist with macrophage infiltration during inflammation and then promote tumorigenesis, suggesting that lower levels of these adipokines may work against neoplastic disease development." (PMID 27983683, 2016). "In addition, IL-6 may also act on other cell types within the tumor microenvironment to enhance tumor growth by supporting angiogenesis and immune escape." (PMID 27006530, 2016). "Indeed, there is increasing evidence that miRNAs might be the link between hypoxia-induced IL6 levels and the enhancement of tumor autophagy." (PMID 27163161, 2016). "Hypoxia may also be involved in increasing TGF-β and IL-6 in tumor cells." (PMID 26910835, 2016). "IL-6 might promote tumour self-seeding by CTCs in clinical situations." (PMID 26623559, 2016). "Univariate analyses revealed that an increase in the IL-6 level was associated with low levels of albumin (<4.0 g/dL), high serum CRP (≥0.5 mg/L), high serum CEA (≥5.0 ng/dL), high serum CA19-9 (≥37 ng/dL), venous invasion, tumor depth of pT4 disease, distant metastasis, and colorectal obstruction." (PMID 26858756, 2016).
tumor (continued). "Indeed, IL-6 is increasingly recognized as the soluble mediator linking chronic inflammation to cancer development, and its protein and mRNA are often overexpressed in serum and tumor samples from breast, bone, liver and colon cancers both in humans and mice." (PMID 27851822, 2016). "In addition to its direct importance to tumor cells, it has been demonstrated a major role of paracrine and autocrine IL-6/STAT3 signaling mediated by cells of the tumor microenvironment in facilitating tumor progression and inflammatory cell-mediated transformation." (PMID 26501341, 2015). "The identification of CRP and LBP in this study and IL-6 previously as indicators of response to radiotherapy suggests that inflammation could be an important factor in radiotherapy response either through tumour response or radiotherapy toxicity." (PMID 26425690, 2015). "It is evident that inflammatory cytokines and chemokines, for example, tumor necrosis factor-alpha (TNF-α), IL-1 and IL-6, and interferon gamma (IFN-γ), which can be produced by the tumor cells and/or tumor-associated leukocytes and platelets, may add directly to the development of malignancy." (PMID 25814785, 2015). "W4P-LHB-mediated production of IL-6 is involved in tumor growth and IL-6 production was significantly lower in female mice; therefore, we tested the hypothesis that estrogen signaling may suppress IL-6 production and inhibit IL-6-mediated tumor growth." (PMID 25645622, 2015). "Thus, a likely explanation of the preponderance of tumor generation in male mice observed in our W4P-injected mouse model is that female hormonal factors play a suppressive role in W4P-induced tumorigenicity by inhibiting IL-6 production." (PMID 25645622, 2015). "However, tumors formed with a mixture of leptin shRNA obASCs and BCCs did not demonstrate similar reduction in IL-6, which suggests that other cells within the tumor microenvironment may be contributing to the increase in IL-6." (PMID 26286584, 2015). "Consequently, the tumor microenvironment could be a source of IL6 detected in the serum of ES patients and paracrine mechanisms are possible to govern apoptotic or disseminating cell fates." (PMID 26215971, 2015). "In addition to the altered apoptotic process and modulation of the DNA repair system, there must be other ways that IL-6 modulates sensitivity/resistance to cisplatin, such as altered drug uptake, drug delivery system and metabolism, or tumor microenvironment changes." (PMID 26313152, 2015). "In tumor-bearing individuals, through interactions between the microbiome and TLR5+ cells that occur at places of bacterial colonization, TLR5 competence drives systemic IL-6 up-regulation, while deficiencies in TLR5 signaling are associated with higher circulating levels of IL-17." (PMID 25897427, 2015). "However, the effect of IL-6 on tumor growth remains debatable." (PMID 25785244, 2015). "Furthermore, we demonstrate that these RF-induced effects occur in various settings (here, in two tumor models, two organs, and two species), are IL6-mediated in these scenarios, and most importantly that they can be reproducibly modulated and attenuated with nano-delivered siRNA." (PMID 26154425, 2015). "Compared with HCC tumor tissue, several EC proliferation and angiogenesis-related genes in peritumoral tissue were gradually up-regulated during seven weeks of tumor growth, including IL-6, IL-6R, and gp130, which was confirmed by RT-PCR (using mouse-specific primers), IHC staining and Western blot." (PMID 26525581, 2015). "Thus, blocking of IL-6 transactivation with sgp130Fc after PDT could increase the therapeutic potential and may be instrumental in elucidating the role of the IL-6 signaling pathway in tumor cell survival." (PMID 26516076, 2015).
tumor (continued). "By engagement of their specific cellular receptors, cytokines such as IL-6 and IL-10 and VEGF activate the JAK2/STAT3 transduction pathway that promotes the transcription of genes encoding for proteins involved in PEL resistance to apoptosis and contributes to tumor survival." (PMID 25695042, 2015). "During the past few years, these activated tumor-associated fibroblasts have also been involved in the modulation of the antitumor immune response, especially by the secretion of soluble immunosuppressive factors in the tumor microenvironment (TGF-β, IL-1β, IL-6, and IL-10)." (PMID 26441986, 2015). "Finally, timing of siRNA administration was compared, and MNP anti-IL6 siRNA administered immediately after hepatic RFA (Day 0) resulted in complete suppression of RFA-induced tumor growth compared to administration at a later time point (3d) after hepatic RFA (Day 0 vs. Day 3, p<0.02)." (PMID 26154425, 2015). "Interestingly, these patients also had high IL6 serum levels indicating that IL6 secreted by ES tumor adjacent fibroblasts could be a major source for IL6 detected in the serum of ES patients." (PMID 26215971, 2015). "In addition, it was also suggested that IL-6 expression in cancer cells could be a useful predictive factor for tumor response to chemoradiotherapy in OSCC." (PMID 25761055, 2015). "Moreover, IL-6 levels increased significantly with increasing local tumor spread (T) (P<0.0001)." (PMID 26082901, 2015). "This suggests that IL6 promotes tumour growth, which may be suppressed by a Th17 and Th2 response." (PMID 25889974, 2015). "Since we have found correlations between ‘Inflammation’ markers and the absence of vaso-invasion, blocking IL-6 might increase the risk of tumour cell invasion." (PMID 25889974, 2015). "Furthermore, IL6 promotes cell dissemination to support evasion from poorly supplied tumor areas." (PMID 26215971, 2015). "However, mice that had received the splenocytes from IL6−/− mice had significantly less lung tumors compared to mice that had received wild-type mouse splenocytes, demonstrating that the IL6−/− splenocytes were more efficient in eliciting an anti-tumor immune response than wild type splenocytes." (PMID 26307977, 2015). "Once binding to IL-6 receptor (IL-6R) and gp130 receptor, IL-6 could activate STAT3, mitogen-activated protein kinase (MAPK) and phosphatidylinositol 3-kinase (PI3K) pathways and increase tumor metastasis, indicating that IL-6 increasing metastasis is IL-6R/gp130 dependent." (PMID 26528698, 2015). "Tumour microenvironment plays a major role in this process, as both infiltrating and tumour cells produce a range of soluble mediators with protumour activity (e.g. interleukin-6, transforming growth factor β, epidermal growth factor and its receptor, vascular endothelial growth factor, etc.)." (PMID 26626416, 2015). "Additionally, studies examining intratumoral heterogeneity found that it can be maintained by interactions between tumor cells, including the up-regulation of IL-6 production in EGFRvIII cells to activate neighboring wtEGFR cells, enhancing tumor growth and resistance to therapy." (PMID 25688333, 2015). "Indeed baseline plasma IL-6 was predictive of benefit with tumour vaccines but also for pazopanib." (PMID 25669986, 2015). "However, a recent study on Forkhead box A (Foxa)-deficient mice showed that the IL-6 level did not correlate with tumour load when Foxa1/2 were only ablated in hepatocytes." (PMID 24708807, 2014). "In addition, deceases on the body weights were also demonstrated in tumor-bearing control with increases of serum IL-6 levels, decreases of periovarian fat pad weights, atrophic changes of white adipose tissues, suggesting tumor-related immunosuppress and cachexia." (PMID 25477992, 2014). "Finally, because the presence of IL-6 and IL-8 in tumor cells may be surrogate markers for ER activation, IL-6 and IL-8 mRNA levels (IL-6, IL-8) were examined." (PMID 25269750, 2014).
tumor (continued). "In addition, increases in IFNγ, IL-6, and IL-12 may contribute to the T cell activation and subsequent antitumor response we observed in mice challenged with A20 tumor." (PMID 24454895, 2014). "In addition, we found that metformin could inhibit IL-6 enhancement of tumor growth, as well as reduce tumor metastasis, through inhibition of STAT3-mediated EMT." (PMID 24789104, 2014). "During tumor development, tumor- and host-secreted factors, including vascular endothelial growth factor, stem cell factor, granulocyte-macrophage colony-stimulating factor, interleukin (IL)-1β, IL-6 and prostaglandin E2, have been reported to promote the accumulation of MDSCs." (PMID 25009656, 2014). "While, we believe that chronic IL-6 expression may be responsible for STAT3 and NFκB downregulation in tumor associated inflammatory cells; its systemic effect may be stimulatory, due to lower concentration in the body compared to the intratumoral concentration." (PMID 25400927, 2014). "Thus, to further delineate the role that stem cells may play in tumor progression through the evasion of hormone-based therapies, IL-6 and IL- 8 gene and protein expression were measured and correlated with ER and PR expression in BCSC." (PMID 25269750, 2014). "We investigated whether the mRNA expression of IL-6 in the control tumor xenografts had any correlation with the mRNA levels of invasion-associated genes such as CXCR4, MMP-2, and MMP-9 in response to systemic administration of paclitaxel and oral gavages of CYT387." (PMID 24782986, 2014). "It has been reported that a high peripheral neutrophil level, which was induced by inflammation-related cytokines (ie, interleukin-6 and tumor necrosis factor) or tumor-derived myeloid growth factors, may indicate systemic inflammation response or a tumor progression." (PMID 24718309, 2014). "Therefore, blocking IL-6 signaling might promote the growth and differentiation of tumor cells by inhibiting anti-tumor immunity." (PMID 25010770, 2014). "The increased expression of IL-6 mRNA observed within the tumor, if translated to protein, could also contribute to an immune-suppressed environment potentially through increased pSTAT3 upregulation within immune cells found in the tumor." (PMID 25436113, 2014). "Soluble factors, such as VEGF, IL-6, and TGFβ, can contribute to reduction of mature DC numbers, expansion and accumulation of immature tolerant DCs, and eventual polarization of DCs toward Th2 or T regulatory (Treg) induction, all features that contribute to tumor evasion from immune response." (PMID 25072019, 2014). "Therefore, we examined the effect of IL-6 on tumor progression in the 4-NQO-treated mice." (PMID 25238263, 2014). "Moreover, silencing of VEGF or IL6 terminates cytokine release in tumor microenvironment." (PMID 24885802, 2014). "IL-6 is a pleiotropic cytokine secreted by the cells of the innate immune system such as DCs, monocytes, macrophages, mast cells, B cells, and a subset of activated T cells, though tumor cells, fibroblasts, endothelial cells, and keratinocytes also secrete IL-6." (PMID 25152827, 2014). "BMP4 induction of IL-6 could enhance the inflammatory tumor microenvironment." (PMID 23840733, 2013). "However, tumor progression is delayed in KrasG12D; IL-6-/- mice, consistent with previous results." (PMID 24260500, 2013). "In addition, exogenous factors from the tumor microenvironment, including hepatocyte growth factor and interleukin-6, may also play a role in primary EGFR TKI resistance." (PMID 24376677, 2013). "In addition, IL-6 has recently been reported to be one of the critical cytokines for inducing suppressive immune cell subsets, such as MDSCs and Th17, which are known to negatively affect anti-tumor immunity." (PMID 23840274, 2013).